TMEM242 (transmembrane protein 242)
Description:
Scaffold protein that participates in the c-ring assembly of mitochondrial ATP synthase (F(1)F(0) ATP synthase or complex V) by facilitating the membrane insertion and oligomer formation of the subunit c/ATP5MC3. Participates in the incorporation of the c-ring into vestigial complexes. Additionally influences the incorporation of subunits MT-ATP6, MT-ATP8, ATP5MJ, and ATP5MK in the ATP synthase.
Synonyms: C6orf35; BM033
Tractability: Antibody: UniProt predicts a signal peptide or a membrane-spanning region. PROTAC: ubiquitination databases record sites on it.
Gene: Protein-coding gene on chromosome 6 (157,289,025 to 157,323,601, reverse strand). Ensembl gene ENSG00000215712.
Subcellular location: Mitochondrion inner membrane
Gene Ontology:
Molecular function: protein binding
Biological process: mitochondrial proton-transporting ATP synthase complex assembly
Cellular component: mitochondrial inner membrane; mitochondrion
Genetic constraint (gnomAD): Loss-of-function variants: 9 observed, 16.83 expected, observed/expected ratio (o/e) 0.53, 90% interval 0.32 to 0.93. The upper end of that interval is the gene's LOEUF score, 0.93, which puts it in group 3 of 6, group 1 being the genes least tolerant of losing a copy. Missense variants: 181 observed, 176.16 expected, observed/expected ratio (o/e) 1.03, 90% interval 0.91 to 1.16. Synonymous variants: 55 observed, 72.9 expected, observed/expected ratio (o/e) 0.75, 90% interval 0.61 to 0.94.
Homologues: Orthologues: chimpanzee TMEM242 (100% identical), mouse Tmem242 (86% identical), guinea pig TMEM242 (84% identical), macaque TMEM242 (82% identical), dog TMEM242 (72% identical), pig TMEM242 (70% identical), rabbit TMEM242 (70% identical), rat Tmem242 (69% identical), tropical clawed frog tmem242 (61% identical), zebrafish tmem242 (60% identical), Drosophila melanogaster CG11699 (32% identical).
Diseases named in the same sentence as TMEM242 in open-access papers:
TMEM242 is named in the same sentence as 2 diseases in open-access papers, as found by Europe PMC text mining. Sharing a sentence is not in itself a finding about the gene and the disease. The quoted sentences say what the papers report.
breast carcinoma (1 paper, 2018). "Of the two consistent genes, Bcar3 is involved in cell proliferation, which when overexpressed in breast cancer conveys estrogen resistance, and Tmem242 is a transmembrane protein with very little current annotation." (PMID 29549885, 2018).
cancer (1 paper, 2022). A tumor composed of atypical neoplastic, often pleomorphic cells that invade other tissues. "Supporting this relationship, the top five co-essential genes with TMEM242 were components of ATP synthase in the Cancer Dependency Map, and in a Seahorse assay, basal respiration was decreased upon TMEM242 knockdown." (PMID 35688146, 2022).